CCND1 (cyclin D1)
Diseases named in the same sentence as CCND1 in open-access papers (continued):
Sharing a sentence is not in itself a finding about the gene and the disease.
pancreatic cancer (continued). "Further, β-catenin activation induced by CCR9 increased the expression of Cyclin E1, Cyclin D1, and E-Cadherin to increase the lethal dose of gemcitabine in pancreatic cancer, suggesting that CCR9/β-catenin signaling enhances pancreatic cancer chemoresistance." (PMID 26879872, 2016). "Immunohistochemical analysis of pancreatic tumor tissues also revealed that UA, alone or in combination with gemcitabine, significantly decreased the expression of cyclin D1, COX-2, VEGF, and MMP-9 molecules compared with the control treatment." (PMID 26909608, 2016). "RV and AC suppressed cell proliferation of human and hamster pancreatic cancer cells by inhibiting the G1 phase of the cell cycle with cyclin D1 downregulation and inactivation of AKT-GSK3β and ERK1/2 signaling." (PMID 26556864, 2015). "PG545 dramatically decreased the levels of β-catenin, phosphorylation of GSK3α/β and its downstream target, Cyclin D1 in all tested pancreatic cancer cells (AsPC-1, MiaPaCa-2, and Capan-1) in a concentration-dependent manner." (PMID 25669977, 2015). "Metformin was reported to decrease SP1/SP3 expression and their downstream targets, such as Bcl-2, survivin, and cyclin D1, in pancreatic cancer cells." (PMID 26294325, 2015). "Our results validated such reports as capsaicin mediated inhibition of β-catenin and TCF-1 signal further inhibited c-Myc and cyclin D1, leading to apoptosis in pancreatic cancer cells." (PMID 25869100, 2015). "In pancreatic cancer cells, E3330 treatment resulted in reduced level of cyclin D1 that is controlled by NF-κB signaling." (PMID 26639148, 2015). "In order to investigate the regulation of cyclin D1 expression in pancreatic cancer cells, we used specific inhibitors of the signal transduction pathways." (PMID 26556864, 2015). "Atorvastatin was also shown to influence the cellular activities of components of the PI3/AKT signaling molecules such as AKT, P2X7, pERK, RhoA, cyclin D1, and β-catenin to inhibit proliferation and induce apoptosis in pancreatic cancer cells." (PMID 26229958, 2015). "Whereas many studies have indicated that STAT-3 regulates cyclin D1, some studies suggest that this transcription factor also alters the expression of other cyclins such as cyclin E in pancreatic cancer and cyclin A in our findings." (PMID 26418031, 2015). "DATS, a garlic-derived organosulfur compound, showed growth inhibitory effects on pancreatic cancer cells (Capan-2) through elevated levels of cyclin B1 and p21 and reduced levels of cyclin D1." (PMID 25401123, 2014). "Together, these results indicate that pancreatic cancer cell proliferation is suppressed with the inhibition of cyclin D1 expression." (PMID 24348824, 2014). "The expression of NR5A2 is also elevated in pancreatic cancer and promotes pancreatic cancer cell growth through stimulation of cyclin D1, cyclin E1 and c-Myc." (PMID 25514243, 2014). "Embelin inhibited the expression of Gli1 and Gli2 and their down-stream target Cyclin D1 in mouse pancreatic cancer cells." (PMID 24694877, 2014). "It was shown in previous study that SFN has inhibited cyclin D1 in pancreatic cancer cells, while cyclin D1-induced Rb overexpression has been found to be upregulated in pulmonary carcinoids." (PMID 23927827, 2013). "In this study, we found that cyclin D1 was required for Six1-induced cell proliferation and tumor growth in pancreatic cancer." (PMID 23527134, 2013). "To summarize, our study demonstrates that Six1 is overexpressed in pancreatic cancer, leading to an increase in cancer cell growth and cell cycle progression through upregulation of cyclin D1." (PMID 23527134, 2013). "Secondly, our data demonstrated that Six1 expression significantly correlates with cyclin D1 in human pancreatic cancer." (PMID 23527134, 2013). "Next, analysis of 27 advanced stage (III & IV) of human pancreatic cancer samples for Six1 and cyclin D1 expression demonstrated a statistically significant correlation between the two (r = 0.541, P = 0.020)." (PMID 23527134, 2013).
pancreatic cancer (continued). "3-Cl-AHPC-induced apoptosis was preceded by decreasing expression of IGF-1R, cyclin D1, β-catenin, and activated Notch-1 in the pancreatic cancer cell lines." (PMID 22570653, 2012). "Our results demonstrated that frankincense essential oil suppresses cyclin D1 and cdk4 proteins expression in pancreatic cancer cells." (PMID 23237355, 2012). "Essential oil activated the caspase-dependent apoptotic pathway, induced a rapid and transient activation of Akt and Erk1/2, and suppressed levels of cyclin D1 cdk4 expression in cultured pancreatic cancer cells." (PMID 23237355, 2012). "We observed that the treatment of pancreatic cancer cells with honokiol resulted in G1-phase arrest of cell cycle progression, along with reduction in cyclin D1, cyclin E, Cdk2 and Cdk4 and increase in p21 and p27 at the protein level." (PMID 21720559, 2011). "Our data suggest that CCND1 and CCND3 associate with unique Rb phosphorylation patterns to mediate a differential effect on global gene transcription in pancreatic cancer cells." (PMID 20113529, 2010). "Our recent studies revealed that mTOR inhibitors such as rapamycin and temsirolimus increase Akt phosphorylation/activation and cyclin D1 expression levels in pancreatic cancer cells." (PMID 20630061, 2010). "We have previously shown that cyclin D1 and E but also cyclin-dependent kinase inhibitors such as p27kip1 are constitutively expressed in human pancreatic cancer cells." (PMID 11953870, 2002). "Creating multi‐marker panels including several biomarkers, such as PCNA, cyclin D1, and Ki‐67, may be a better way to predict patient outcomes and direct therapy choices for pancreatic cancer." (PMID 40051490, 2025). "Moreover, the overexpression of cyclin D1 in pancreatic cancer is correlated with a reduced postoperative survival rate." (PMID 40051490, 2025). "Additionally, overexpression of cyclin D1 can lead to resistance of pancreatic cancer to cytotoxic drugs chemotherapy." (PMID 40051490, 2025). "Cyclin D1 suppression levels can enhance the response of pancreatic cancer cells to cisplatinum." (PMID 40051490, 2025). "Based on data that has attributed cellular functions to fibroblast proliferation in other tissues, we investigated a panel of ten central regulators of cell proliferation (c-Myc, Cyclin D1, Cyclin E1, FGF2, FGFR2, EGFR, EGF, FGF1, FGFR1 and VEGFA) in pancreatic cancer-associated fibroblasts (CAFs)." (PMID 38678032, 2024). "Our finding that SEMA6C-low pancreatic cancer showed increased cyclin D1 expression motivated us to test whether CDK4/6 inhibitors may have therapeutic benefits on pancreatic cancer with the downregulation of SEMA6C." (PMID 35269749, 2022). "Moreover, compound 2 was found to induce apoptosis mediated by the activation of Wnt5a/Cyclin D1 signaling pathway in human pancreatic tumor cells." (PMID 36225350, 2022). "MiR-584 targets CCND1 to inhibit invasion and proliferation of pancreatic carcinoma." (PMID 36118276, 2022). "YTHDF2 inhibited adhesion, invasion, migration, and Epithelial-Mesenchymal Transition (EMT) through the YAP signal and promoted the proliferation of pancreatic cancer cells through the Serine/threonine-protein kinases/Glycogen synthase kinase 3 beta/Cyclin D1 (AKT/GSK3B/CCND1) pathway." (PMID 33692959, 2021). "Over-expression of Cyclin D1 was found to confer gemcitabine and cisplatin resistance to pancreatic cancer cell; CCNE1, CDK2, and CDKN1A, previously reported to be up-regulated by gemcitabine as confirmed in our study, were also implied in chemotherapy resistance." (PMID 33925948, 2021). "In particular, it was shown that miRNA-720 inhibits pancreatic cancer cell proliferation and invasion by directly targeting cyclin D1 so that down-regulation of miRNA-720 as observed in PDAC patients compared to healthy individuals has a potential tumor-promoting effect." (PMID 34368146, 2021).
pancreatic cancer (continued). "The results demonstrated that silencing circSEC24A expression resulted in protein downregulation of CDK4, CDK6 and Cyclin D1, indicating that inhibited circSEC24A could negatively modulate pancreatic cancer cell proliferation." (PMID 34906151, 2021). "SOX2OT/FUS promotes pancreatic cancer via regulation of cyclin D1 (CCND1) and p27 expression." (PMID 33050646, 2020). "Moreover, recent studies have revealed that CCND1 was up-regulated in pancreatic cancer tissues and validated as a direct binding target of miR-720/miR-584 to inhibit cell proliferation and invasion." (PMID 32537471, 2020). "Taken together, these studies suggest KLF5 may promote cyclin D1 gene expression directly by binding to its promoter in pancreatic cancer cells." (PMID 31327760, 2019). "Silencing of galectin-3 decreased pancreatic cancer cell proliferation and cyclin-D1 levels." (PMID 31832021, 2019). "We also found that ISL1 could upregulate cyclin D1, cyclin B, and c-Myc, which was in agreement with previous reports on pancreatic cancer cells." (PMID 30674889, 2019). "Moreover, IRF-2 has been found to modulate the growth of pancreatic cancer cells by regulating proliferation and apoptosis effectors, such as cyclin D1 and BAX." (PMID 28465494, 2017). "Furthermore, canertinib and afatinib treatment also inhibited proliferation, migration and survival of pancreatic cancer cells by attenuation of signaling events including pERK1/2 (T202/Y204), cyclin D1, cyclin A, pFAK (Y925) and pAKT (Ser473)." (PMID 25686822, 2015). "Furthermore, it has been reported that treatment with beta-adrenergic antagonists significantly suppresses the expression of p-ERK, Akt, Bcl-2, and cyclin D1, and induces the activation of caspase-3, caspase-9, and Bax in cultured pancreatic cancer cells." (PMID 25742648, 2015). "Cyclin D1 is upregulated in pancreatic cancer tissues compared with surrounding normal tissues." (PMID 24348824, 2014). "The arrest of cell cycle in the G1 phase and downregulation of cyclin-D1 suggest that α-mangostin may downregulate the activity of the PI3K/Akt pathway in pancreatic cancer cells." (PMID 24812621, 2014). "Similarly, in the present study, pancreatic cancer cell proliferation and the expression of cyclin D1 were suppressed following siRNA- and shRNA-Fz2 treatment, the latter as revealed by quantitative PCR analysis." (PMID 24348824, 2014). "In addition, Curcumin has been shown to suppress the expression of cyclin D1 in many types of cancer including head and neck, colon, bladder, breast, cervical and pancreatic carcinomas." (PMID 25866478, 2014). "In pancreatic tumor cells, over-expression of cyclin D1 also dramatically reduced chemosensitivity and prolonged survival time upon cisplatin treatment, and knockdown of cyclin D1 resulted in impaired resistance to cisplatin-induced apoptosis." (PMID 23806108, 2013). "To determine whether both Six1 and cyclin D1 are coordinately expressed in pancreatic cancer, we examined their protein expression in the xenograft tumors from PANC-1 cells stably transfected with either Six1 or control plasmids." (PMID 23527134, 2013). "Taken together, these results suggest that Six1 may also promote cyclin D1 expression in human pancreatic cancer." (PMID 23527134, 2013). "In addition, combined treatment of 9-cis and troglitazone, decreased cyclin D1 expression in pancreatic cancer." (PMID 24098526, 2013). "Thirdly, the growth advantage conferred by Six1 in pancreatic cancer cells is cyclin D1-dependent." (PMID 23527134, 2013). "Frankincense essential oil suppressed cyclin D1 and cdk4 expression may lead to suppressed Rb phosphorylation which results in suppressed cell cycle progression in pancreatic cancer cells." (PMID 23237355, 2012). "In addition, frankincense essential oil modulated expression of cell cycle regulator proteins, cdk4 and cyclin D1 (crucial cell cycle regulators), in pancreatic cancer cells." (PMID 23237355, 2012).
pancreatic cancer (continued). "Furthermore, essential oil suppressed cyclin D1 expression almost immediately, within 15 min, after treatment in all four pancreatic cancer cell lines." (PMID 23237355, 2012). "In addition, overexpression of cyclin D1 is a frequent feature of neoplasias, and serves as a prognostic marker in pancreatic cancer." (PMID 22443451, 2012). "Inhibition of cyclin D1 expression has been found to inhibit pancreatic cancer growth." (PMID 22570653, 2012). "Heatmap analysis in colorectal, stomach, and pancreas cancer patient datasets showed a consistent overlap between LBH overexpression and WNT signaling genes associated with pathway activation, i.e., WNT2, WNT5A, WNT11, LEF1, TCF4 or TCF7, CCTNB1, CCND1, JUN, DKK3." (PMID 37268816, 2023). "Study of pancreatic cancer in nude mice has shown that curcumin can suppress pancreatic cancer cell proliferation and angiogenesis by inhibiting NF-ĸB-regulated gene products such as cyclin D1, cmyc, Bcl-2, Bcl-xL, and apoptosis protein-1, COX-2, MMP, and vascular endothelial growth factor (VEGF)." (PMID 27618095, 2016). "Indeed, as shown in pancreatic cancer cells, EGF stimulation leads to tyrosine phosphorylation of Vav1, followed by the activation of a Rac1/Pak1/NF-κB signaling pathway resulting in an increase in cyclin D1 which leads to enhanced pancreatic tumor cell proliferation." (PMID 26353933, 2015). "Furthermore, TCGA data portal shows that human PDACs exhibit amplifications and mutations in ADAM10, MYC, VIM (vimentin), CD44, CCND1 (CyclinD1) and CTNNB1 (β-catenin), implying the importance of interfering with the signaling associated with these in prevention of pancreatic cancer." (PMID 26440150, 2015). "However, after DKK3 transfection, consistent with the results reported by Xiang, we also found that DKK3 inhibits the nuclear accumulation and the activation of β‐catenin and its downstream genes cyclin D1, c‐Myc in pancreatic cancer Bxpc‐3 cell in normoxia and hypoxia." (PMID 26395974, 2015). "As the results show above, the expression of cyclin D1 is significantly inhibited, and we assumed that the water decoction of Taxus cuspidate may disrupt the wnt/β-catenin cell signaling to inhibit the proliferation of pancreatic cancer." (PMID 24719642, 2014). "Furthermore, we examined the expression of Six1 and cyclin D1 in three other independent pancreatic cancer microarray datasets and all of them showed a significant correlation between the two (GSE15471: r: 0.477, P = 0.0021; GSE32676: r: 0.372, P = 0.036; and GSE28735: r: 0.767, P<0.0001)." (PMID 23527134, 2013). "Likewise, GATA3 can be overexpressed in pancreatic cell lines and primary pancreatic cancers, and in neuroblastoma cell lines, where it positively regulates cyclin D1, maintaining cells in an undifferentiated state, therefore suggesting an oncogenic potential for GATA3 in neuroblastoma." (PMID 24205108, 2013). "Thus, the induction of PDGFs and cyclin D1 in pancreatic cancer cells by TGF-β1 has been reported." (PMID 11870516, 2002). "In conclusion, E2F1 promotes pancreatic cancer cell proliferation and cell-cycle progression by upregulating WDHD1, which in turn enhances the expression of the CDK4-cyclin D1 complex." (PMID 42041705, 2026). "Since Ki‐67, Cyclin D1, PHH3, and PCNA are key proliferative markers in pancreatic cancer, our review focuses extensively on them." (PMID 40051490, 2025). "Overall, Ki‐67, Cyclin D1, PHH3, and PCNA biomarkers can potentially improve pancreatic cancer clinical management by providing valuable information about disease progression and treatment response." (PMID 40051490, 2025).
pancreatic cancer (continued). "We conducted a narrative review by searching Scopus, PubMed, and Google Scholar for studies focusing on Ki‐67, PCNA, Cyclin D1, and PHH3 in relation to pancreatic cancer and chemotherapy." (PMID 40051490, 2025). "This review explores the potential role of proliferative markers, including Ki‐67, PCNA, Cyclin D1, and PHH3, as predictive and prognostic indicators in pancreatic cancer management, aiming to enhance personalized treatment strategies." (PMID 40051490, 2025). "In another study it was found that MIF increased pancreatic cancer progression and metastasis via AKT/ERK (Extracellular signal-regulated protein kinases)/CCND1 (Cyclin D1)/MMP-2 (Matrix metalloproteinase-9) axis." (PMID 41159021, 2025). "The use of proliferative markers such as Ki‐67, Cyclin D1, PHH3, and PCNA has garnered increasing attention for their potential as prognostic and predictive tools in cancer treatment, including pancreatic cancer." (PMID 40051490, 2025). "Proliferative markers (Ki‐67, PCNA, Cyclin D1, PHH3) serve as valuable indicators of pancreatic cancer behavior and treatment response." (PMID 40051490, 2025). "Proliferative markers such as Ki‐67, PCNA, Cyclin D1, and PHH3 hold potential as predictive and prognostic tools in pancreatic cancer management." (PMID 40051490, 2025). "PROK1 knockdown also inhibited the proliferation of pancreatic cancer cells, characterized by a decrease in PCNA and cyclin D1 levels, leading to slow growth of PC in vivo." (PMID 37070074, 2023). "For example, cucurbitacin I reduces the levels of p-JAK2 and p-STAT3 proteins and decreases the expression of CCND1 and CCNA2 in pancreatic cancer cells." (PMID 37958903, 2023). "The results showed that GPRC5A was closely correlated with CYR61, cyclin D1, c-Myc, and CTGF in pancreatic cancer." (PMID 36735162, 2023). "Our results showed that PROK1 knockdown inhibited pancreatic tumor growth in vivo and reduced proliferating markers, such as PCNA and cyclin D1, at the molecular level." (PMID 37070074, 2023). "The results showed that GPRC5A positively regulated YAP1, CYR61, cyclin D1, c-Myc and CTGF expression at the transcriptional level, as evidenced by overexpression and knockdown of GPRC5A in pancreatic cancer cells." (PMID 36735162, 2023). "Multiple genes regulated by YAP1 are related to the unfavorable survival of pancreatic cancer patients, such as FOSL1, CCND1, and NOTCH2." (PMID 36735162, 2023). "FOXM1 induces pancreatic cancer cell growth, migration, and invasion by increasing the expression of CCNB1, CCND1, CDK2, MMP2, MMP9, and VEGF, and activates mesenchymal cell markers promoting EMT." (PMID 37239940, 2023). "Next, we explored correlation between E2F4, CCNE1, CCND1 and NOP14 in pancreatic cancer tissue in TCGA database." (PMID 37506248, 2023). "And finally, CCND1 and MAPK1 were found to be prognostic factors in patients with pancreatic cancer." (PMID 35039759, 2022). "Overexpression of INSM1 inhibits the binding of cyclin D1 and CDK4, induces cell cycle arrest, and inhibits the growth of panc-1 pancreatic cancer cell line." (PMID 36531655, 2022). "Over-expression of KIF15 increases the cyclin-D1, CDK2, p-RB expression, and accelerated G1/S transition in pancreatic cancer cells." (PMID 35359374, 2022). "By analysing the TCGA database, we found that the expression of PCDH1 was positively correlated with CCND1, CCNE2, VEGFA, MET, CD44 and CD133 expression in pancreatic cancer tissues." (PMID 35864095, 2022). "In SEMA6C-downregulated pancreatic cancer, the enhancement of AKT activity induced the accumulation of nuclear β-catenin to promote the expression of cyclin D1 and stimulated cell growth." (PMID 35269749, 2022).